PPARG (peroxisome proliferator activated receptor gamma)
Diseases named in the same sentence as PPARG in open-access papers (continued):
Sharing a sentence is not in itself a finding about the gene and the disease.
Sepsis (continued). "Furthermore, the focus will be directed towards the potential role of PPARγ agonism in alleviating muscle inflammation and metabolic disturbances during sepsis." (PMID 34575939, 2021). "Pioglitazone use via the PPARγ agonist in sepsis patients is inconclusive." (PMID 34394992, 2021). "PPARγ controls inflammation by both negatively modulating the production of pro-inflammatory cytokines and enhancing the synthesis of anti-inflammatory cytokines during sepsis." (PMID 32599864, 2020). "Oral gavages of probiotics (VSL#3) have been shown to prevent the breakdown of intestinal barrier integrity, reducing the translocation of gut bacteria and liver injury in a sepsis mouse model via peroxisome proliferator-activated receptor gamma- (PPARγ-) dependent mechanisms." (PMID 31001563, 2019). "Mitochondrial ROS formation in CGD cases might be beneficial for clearance of recurrent infections as PPARγ agonists play a role in infection clearance in sepsis cases." (PMID 31428088, 2019). "Peroxisome proliferator-activated receptor gamma (PPARγ) is a major regulator in sepsis." (PMID 31888703, 2019). "Although a previous study has assessed the association between the Pro12Ala polymorphism of PPARγ and sepsis mortality, little was known about the clinical relevance of other SNPs in PPAR family genes in relation to the development of sepsis and MODS in trauma patients." (PMID 27023591, 2016). "PPARγ signaling has shown a protective effect in multiple models of sepsis." (PMID 27774097, 2016). "Since neutrophil expression was increased in septic patients and mice, the authors of the study suggested that the inhibited migration of neutrophils during sepsis might occur as a result of PPARγ activation." (PMID 22481914, 2012). "Of particular interest is the possibility that ligand activation of PPARγ may participate in the pathophysiology of sepsis." (PMID 23316104, 2012). "TNF-α is also known to downregulate PPARγ function by several mechanisms (see Ye 2008 for a recent review), and LPS treatment was shown to downregulate PPARγ expression in Kupffer cells both in vitro and in an animal model of sepsis through a TNFα -dependent mechanism." (PMID 19756185, 2009). "Furthermore, PPARγ activation may reduce neuronal death, thus improving the life quality of patients who recovered from sepsis, who often live with sequelae for long periods." (PMID 35563317, 2022). "But in sepsis, it had been reported that the chemotaxis of neutrophils could be interrupted by several elements such as highly concentrated cytokines and chemokines, peroxisome proliferator-activated receptor-γ (PPARγ), and some other elements." (PMID 35003233, 2021). "GE might develop its protective role in sepsis-induced kidney injury through activation of PPARγ." (PMID 33197894, 2020). "Furthermore, the therapeutic effects of GE on sepsis model in vivo and in vitro may act by activating PPARγ." (PMID 33197894, 2020). "The activation of PPARγ might be the molecular mechanism involved in which a fish oil-enriched diet maintains balanced Th polarization, mitigates inflammation, and alleviates exacerbated inflammation in sepsis." (PMID 32599864, 2020). "In addition, PPARγ has been proved to hamper inflammation response in sepsis." (PMID 33197894, 2020). "Further, PPARγ could affect the NF-κB signaling pathway and the downstream proinflammatory cytokines, which were seen as important factors during the development of sepsis and MODS." (PMID 27023591, 2016). "Among sepsis patients, ABCC1 was identified as a low-expression gene, while CYP1B1 and PPARG were identified as high-expression genes." (PMID 41509654, 2026). "The AUROCs for diagnosing sepsis using MAPK8, PTEN, PPARG, and STAT3 were calculated as 0.808 (95% CI 0.586–1.000), 0.842 (95% CI 0.643–1.000), 0.883 (95% CI 0.713–1.000), and 0.85 (95% CI 0.652–1.000), respectively." (PMID 40070882, 2025).
Sepsis (continued). "In conclusion, our study successfully identified MAPK3, MAPK8, PPARG, PTEN, and STAT3 as potential ferroptosis-related genes involved in the progression of sepsis." (PMID 40070882, 2025). "The AUROCs of MAPK3, MAPK8, PPARG, PTEN in the diagnosis of sepsis were 0.751, 0.611, 0.781, 0.618, and 0.857, respectively." (PMID 40070882, 2025). "In line with our endeavor to “unveil the glycolysis in sepsis,” the discovery of IER3, DSC2, and PPARG reinforces their cardinal roles in sepsis pathogenesis." (PMID 39331858, 2024). "In a mouse model of LPS-induced sepsis-induced lung injury, reducing TRIM27 was found to alleviate sepsis-induced inflammation, oxidative stress, and cell apoptosis by inhibiting PPARγ ubiquitination and decreasing NADPH oxidase 4 (NOX4) expression." (PMID 39234245, 2024). "In patients died from sepsis, the expression levels of COMT and PTGS2 were significantly elevated, PPARA and PPARG were significantly decreased." (PMID 38641695, 2024). "In conclusion, our exploration underscores the pivotal role of glycolysis in sepsis, emphasizing the significance of IER3, DSC2, and PPARG." (PMID 39331858, 2024). "We further examined the expressions of rate-limiting enzyme CPTI and related molecules PPARα and PPARγ as well as its cofactors PGC-1α and PGC-1β to determine FAO levels in WT and TREM2–/– sepsis mice." (PMID 39405126, 2024). "Other biomarkers also correlate with outcome/prognosis e.g., CD177, FGF13, GRB10 and PPARG in both SIRS and sepsis." (PMID 38332914, 2023). "Our results indicated that increased expression of PPARγ reduced ROS levels and inhibited the TXNIP/NLRP3 signaling pathway, resulting in decreased pyroptosis and reduced liver dysfunction during sepsis." (PMID 35136484, 2022). "In conclusion, the current findings demonstrated that the activation of PPARγ reduced ROS levels and inhibited the TXNIP/NLRP3 signaling pathway to decrease pyroptosis and reduce liver damage during sepsis." (PMID 35136484, 2022). "Several studies have shown that the PPARγ agonists, such 15d-PGJ2, ciglitazone, and pioglitazone, confer protection in neuroinflammatory and sepsis animal models through the inhibition of STAT, AP-1, and NF-κB activity as well as reduced Th1 differentiation." (PMID 33256749, 2020). "Pioglitazone, another PPARγ agonist, has been shown to reduce inflammation and improve survival in a murine CLP and Candida albicans-induced sepsis." (PMID 32547553, 2020). "Thus, the activation of PPARγ was considered as an optional approach for ameliorating organ damage by inhibiting inflammation and apoptosis, which might be the main approach for the protective role of GE in sepsis-induced AKI in this study." (PMID 33197894, 2020). "We hypothesized that PPARγ inhibits overproduction of ROS by promoting Nrf2 expression to reduce NLRP3-mediated pyroptosis and alleviates sepsis-induced liver injury." (PMID 35136484, 2022). "Dusp, SphK1, IL10, ATF4, VEGF, CEBP, PGC1a, and PPARg were not significantly affected by sepsis (data not shown)." (PMID 32477273, 2020). "Here, we demonstrate that PPARs are involved in the regulation of LPS-induced HMGB1 release in RAW 264.7 cells, and the administration of rosiglitazone, a specific ligand for PPARγ, attenuated endotoxin lethality by inhibiting HMGB1 release in a mouse model of sepsis." (PMID 23316104, 2012). "Here we evaluated hemodynamic and renal consequences of separate and combined PE and sepsis insults in weaning mothers and tested whether this interaction is influenced by prenatally-administered losartan (AT1-receptor blocker) or pioglitazone (PPARγ agonist)." (PMID 40057533, 2025). "This may not always be a beneficial response, as sepsis patients have higher expression of PPARγ, and blocking PPARγ reverses sepsis-induced inhibition of neutrophil chemotaxis." (PMID 26713087, 2015).
Sepsis (continued). "Top ranked hits included FAM20A, PPARG, ADM and ARG1, many of which are commonly expressed in both SIRS and sepsis disease groups relative to controls and are non-specific." (PMID 38332914, 2023).
hyperlipidemia (96 papers, 2007 to 2026). "Biochanin A activates PPARγ/LXRα/ABC transporter and PPARγ/heme oxygenase 1 signaling pathways to suppress hyperlipidemia-induced inflammation in ApoE-deficient mice." (PMID 38699583, 2024). "Decreased forkhead box O1 (FoxO1) activity induces hyperlipidemia and increased PPARγ, leading to hyperlipidemia in association with endoplasmic reticulum (ER) stress." (PMID 31235676, 2019). "Therefore, modulating PPARγ's function in the osteoblast could be a potential target for combating bone loss associated with hyperlipidemia." (PMID 33071983, 2020). "Coffee-derived trigonelline, an alkaloid derivative of niacin (vitamin B3), alleviates hyperlipidemia by increasing PPARα and decreasing PPARγ expression." (PMID 38699583, 2024). "During the process of lipid regulation in zebrafish, the downregulation of Pparγ and Rxrα positively impacted zebrafish hyperlipidemia." (PMID 38474201, 2024). "Altogether, these results suggest that PPARγ activation during hyperlipidemia protects the aortic valve against excessive inflammation." (PMID 36115863, 2022). "Here the authors perform single-cell RNA sequencing to show the immunomodulatory role of PPARγ in valvular endothelial cells during hyperlipidemia." (PMID 36115863, 2022). "While PPARγ inhibition promotes valvular inflammation, the activation of PPARγ protects the aortic valve from excessive inflammation during hyperlipidemia." (PMID 36115863, 2022). "PPARγ agonists, including troglitazone, rosiglitazone, ciglitazone, and pioglitazone, have been used in the treatment of hyperlipidemia and hyperglycemia." (PMID 36359869, 2022). "Meanwhile, activated PPARγ exerted a protective role in the early inflammatory phase of aortic valve disease induced by hyperlipidemia, suggesting PPARγ as a putative drug target for aortic valve disease." (PMID 36115863, 2022). "In summary, 6 weeks of administration with CO inhibited the serum BCAA concentration, and further suppressed the expression of the liver PPARγ, thus improving hyperlipidemia in HFD mice." (PMID 35745155, 2022). "The downregulation of key HDL proteins in the small intestine in hyperlipidemia is due to decreased levels of their transcriptional activators PPARγ, LXRs, and SIRT1." (PMID 34944413, 2021). "In agreement with our results, some mammal studies have demonstrated that CA and HT regulate WAT mass by suppressing lipogenic enzyme activity and claimed that PPARγ antagonists can be used to treat hyperlipidemia." (PMID 28570659, 2017). "PPARγ is also a drug target and, currently, its synthetic ligands are used to treat hyperlipidemia and as insulin-sensitizing antidiabetic agents." (PMID 24790595, 2014). "The aim of the current study was to examine the effect of folic acid (FA) and vitamin B12 (VB12) on the mRNA expression of PPARγ, and caspase-3 and -8 in the abdominal aortas of rats with hyperlipidemia." (PMID 23935743, 2013). "Our data suggest that EWGP lowers hyperlipidemia of C57BL/6 mice induced by high-fat diet via the inhibition of PPARγ and HMGCR signaling." (PMID 23533476, 2013). "In clinical practice, PPARα agonists (fibrates) are used to treat hyperlipidemia, whereas PPARγ agonists (TZDs) are used to increase insulin sensitivity in muscle and adipose tissue." (PMID 20811644, 2010). "The notable increase in Pparα and decrease in Pparγ in the liver after CSE intervention suggests that CSE could reduce lipid accumulation in hyperlipidemia mice." (PMID 40077474, 2025). "Notably, metabolic DEGs such as ACSL1, ABCA1, ABCG1, ACAT2, ALOX5AP, PLA1A, and PPARG were elevated in hyperlipidemia." (PMID 39853712, 2025). "Indeed, a previous study indicated that low-dose aspirin alleviates hyperlipidemia by reducing the transcript levels of PPARγ, the master regulator of adipogenesis." (PMID 39859567, 2025). "Similarly, Saccharina sculpera-derived fucoidans improve hyperlipidemia potentially by enhancing the gene expression of PPARα and PPARγ in Wistar rats." (PMID 38699583, 2024).
hyperlipidemia (continued). "Betaine attenuates hyperlipidemia by activating PPARα and PPARγ and their downstream gene LXRα." (PMID 38699583, 2024). "Indeed, PPARγ crucially regulates hepatic lipid uptake and liver-specific Pparg-null mice exhibit aggravated hyperlipidaemia and insulin resistance." (PMID 35883786, 2022). "The network analysis uncovered that naringenin, isorhamnetin, and taxifolin might be the compounds in DO that are mainly in charge of its roles in hyperlipidemia and might play a role by modulating the targets (including PPARG, ADIPOQ, AKT1, TNF, and APOB)." (PMID 35502176, 2022). "The reduction of Citicoline and Isoferulic acid in CO mice may contribute to the inhibition of PPARγ expression, and hyperlipidemia induced by a high-fat diet." (PMID 35745155, 2022). "A final mechanism by which hyperlipidemia could impact osteoblast performance and skeletal homeostasis is through the activation of PPARγ, a transcriptional regulator of adipogenesis that can be activated by elevated lipid levels." (PMID 33071983, 2020). "Previous studies have reported that statins may improve hyperlipidemia and enhances femoral head neovascularization through suppresses PPARγ expression and activates Wnt3a/LRP5/b-catenin/RUNX2 signaling pathway in steroid-induced animal models." (PMID 32509867, 2020). "Hence, MDG-1, as a regulator of PPARα and PPARγ, possesses significant importance in a myriad of biochemical processes such as the regulation of blood lipid metabolism and hyperlipidemia." (PMID 28885549, 2017). "Our data suggested that MDG-1 was a PPARα agonist and a PPARγ antagonist; it could moderate the PPARs pathway, therefore ameliorating hyperlipidemia in HFD-fed mice." (PMID 28885549, 2017). "Because recent evidence suggests that the mTORC1 plays a critical role in PPARγ-mediated adipogenesis, fat accretion, and lipemia, n−3/n−6 ratio elevated intrinsically in fat-1-APCMin/+ mice might lower serum lipids via suppression of mTORC1." (PMID 27769066, 2016). "In order to prevent and mitigate the high-fat state that results from endothelial injury, this study examined the effect of folic acid (FA) and vitamin B12 (VB12) on the expression of PPARγ and caspase-3 and -8 mRNA in the abdominal aortas of rats with hyperlipidemia." (PMID 23935743, 2013). "Geraniol activates both PPARγ and PPARα thereby improving hyperlipidemia and glucose uptake." (PMID 23176672, 2012). "Interestingly, polysaccharides may suppress hyperlipidemia-induced inflammation by decreasing PPARγ in hyperlipidemic animals." (PMID 38699583, 2024). "Additionally, polyphenols can influence the activity of peroxisome proliferator-activated receptor gamma (PPAR-γ), a nuclear receptor that plays a critical role in lipid metabolism and adipocyte differentiation, potentially reducing hyperlipidemia and its associated cardiovascular risks." (PMID 39590851, 2024). "Therefore, it is suggested that 6-gingerol reduces the extent of lipogenesis by downregulating lipogenic transcription factors, such as SREBP-1, PPARγ, and C/EBPα, leading to a reduced expression of FAS, which, in turn, attenuates hyperlipidemia associated with adiposity." (PMID 37571394, 2023). "Genes related to the PPAR pathway and lipid peroxidation were significantly (P < 0.05) upregulated (PPARγ) or downregulated (PPARα, CPT1A, ACOX1) in the liver of hyperlipidemia group." (PMID 41144456, 2025). "For example, sea buckthorn flavonoids improve hyperlipidemia by up-regulating PPARα/CPT-1α and PPARγ/ABCA1 signaling pathways." (PMID 38699583, 2024). "After exploring the PPI network of DO for hyperlipidemia, the key targets of DO for hyperlipidemia included AKT1, TNF, PPARG, ADIPOQ, and APOB." (PMID 35502176, 2022). "Hyperlipidemia may lead to endothelial injury, due to its effects on homocysteine and vascular endothelial growth factor in the serum, and the mRNA expression levels of peroxisome proliferator-activated receptor-γ (PPARγ), and caspase-3 and -8 in the vascular wall." (PMID 23935743, 2013).
hyperlipidemia (continued). "In summary, AKT1, TNF, PPARG, ADIPOQ, and APOB may be targets for the action of DO in the treatment of hyperlipidemia." (PMID 35502176, 2022). "Compared with the HFD group, we found that the mRNA expression levels of PPARα were significantly increased, whereas the gene expression levels of PPARγ were suppressed observably with MDG-1 intervention, implying that MDG-1 could improve hyperlipidemia through regulating PPARs signaling." (PMID 28885549, 2017).